P2RX1 (purinergic receptor P2X 1)
Diseases named in the same sentence as P2RX1 in open-access papers (continued):
Sharing a sentence is not in itself a finding about the gene and the disease.
tumor (19 papers, 2009 to 2025). "Taken together, the results from our in vivo PDAC liver metastatic model confirmed that P2RX1 deficiency promoted tumor growth and immune exhaustion in the liver." (PMID 33420030, 2021). "Critically, our preliminary study from Ph+ ALL patient cohorts revealed that low expression of P2RX1 is significantly associated with inferior prognosis, suggesting that P2RX1 may function as a tumor suppressor in this disease." (PMID 41458092, 2025). "P2rx1+ neutrophils are associated with positive anti-tumor responses and inflammation." (PMID 40568084, 2025). "In addition, tumor growth in the livers of P2rx1−/− mice was remarkedly impaired to a comparable level as that in WT mice, suggesting that the promotional effects of P2RX1 deficiency on liver metastases was related to neutrophils." (PMID 33420030, 2021). "This phenotype was reversed at a later timepoint which coincided with downregulation of immunosuppressive Cd274+Lcn2+ neutrophils and upregulation of anti-tumor P2rx1+Nrf2− neutrophils." (PMID 40568084, 2025). "Methylation analysis showed the methylation of P2RX1 was significantly higher in tumor than in normal samples." (PMID 37795779, 2023). "But real-time quantitative reverse transcription PCR (RT-qPCR) and Western blot detected that the P2RX1 expression in normal mammary epithelial cells was lower than that in tumor cells." (PMID 35585027, 2022). "Among them, P2RX1 expression was significantly lower in 12 tumor tissues types compared with the para-cancerous tissues." (PMID 35585027, 2022). "Then we analyzed the P2RX1 expression between normal and tumor tissues using the TCGA database and the Genotype-Tissue Expression (GTEx) database, and similar results showed that P2RX1 is lowly expressed in a variety of tumors." (PMID 35585027, 2022). "P2RX1 belongs to a family of ATP-gated trimeric ion channels and is expressed on the surface of a variety of cells, including neutrophils, tumor cells, and smooth muscle cells." (PMID 35585027, 2022). "GO analysis revealed that the tumor growth and immunosuppression pathways were upregulated in P2rx1−/− mice." (PMID 33420030, 2021). "We simultaneously added external ATP-assisted Dex and Imatinib and combination therapy to the control group and found that apoptosis was increased, which further verified the relationship between the activation of the P2RX1 channel and the prognosis of the tumor." (PMID 41502525, 2025). "This study reveals the role of P2RX1 as a calcium-regulated tumor suppressor in Ph+ ALL, promoting apoptosis by disrupting mitochondrial function and inhibiting the PI3K/Akt survival signaling pathway, thereby providing a novel therapeutic approach to overcome TKI resistance." (PMID 41458092, 2025). "This study investigated the tumor-suppressive role of P2RX1 in Ph+ ALL." (PMID 41458092, 2025). "This study indicated that P2RX1 is significantly positively correlated with tumor-infiltrating immune cells and their biomarkers in BC, including B cell, CD8+ T cell, CD4+ T cell, macrophage, neutrophil, and dendritic cell, revealing the important role of P2RX1 in BC immune modulation." (PMID 35585027, 2022). "Data from GIPIA showed results similar to those from the TIMER database which suggested P2RX1 may participate in the process of tumor immunomodulation." (PMID 35585027, 2022). "The expression of P2RX1 is abundant on TILs in some tumor types, so P2RX1 may be correlated with the TME." (PMID 35585027, 2022). "The roles of ADORA2B in promoting tumor metastasis have been well characterized; however, the roles of P2RX1 in PDAC progression or metastasis remain unknown." (PMID 33420030, 2021). "Therefore, it is possible that the increase in P2rx1+Nrf2− neutrophils in our model could have a beneficial effect for the host which is consistent with the decreased primary tumor growth rate and reduced metastasis observed in vivo." (PMID 40568084, 2025). "Moreover, activating P2RX1 expressed by tumor cells also impacts tumor growth." (PMID 35585027, 2022).
tumor (continued). "Among them, the expression of CHRDL1, P2RX1, GCSAML, and APOC4-APOC2 in the tumor region was significantly lower than that in the normal region." (PMID 40860241, 2025). "In TCGA-LUAD cohort, the expressions of CHRDL1, P2RX1, GCSAML and APOC4-APOC2 in tumor tissues were significantly lower than those in normal tissues, indicating the tumor-suppressing role of these genes in LUAD." (PMID 40860241, 2025). "Specifically, the Purinergic genes P2RX1 and GNAI2 have significant roles in promoting the EMT process of tumor cells, while P2RY13 can inhibit the progression of the tumor cell cycle." (PMID 38180750, 2024). "The differential gene enrichment analysis revealed that pathways such as ATP-dependent ion channels, calcium binding, death receptor, and tumor necrosis factor-activated receptor pathways were activated in P2RX1 high SUP B15, which were correlated with good tumor prognosis." (PMID 41502525, 2025). "Transcriptome differential expression analysis showed that P2RX1 was significantly down‐regulated in tumor compared with normal samples." (PMID 37795779, 2023). "The mRNA expression of P2RX1 was analyzed to identify the differential expression in normal and tumor tissues." (PMID 35585027, 2022). "P2RX1 expression was significantly positively correlated with PDCD1 (r = 0.507, p = 3.84e-66), CTLA4 (r = 0.455, p = 6.07e-52) and CD274 (r = 0.351, p = 3.26e-30) in BC after adjusted by tumor purity." (PMID 35585027, 2022). "The results showed that P2RX1 predominantly colocalized with neutrophil markers in adjacent liver tissues but was absent from neutrophil markers in metastatic tumor tissues." (PMID 33420030, 2021). "Here the authors show that a subset of P2RX1-negative neutrophils with immunosuppressive properties accumulate in PDAC metastatic liver tissues and promote tumor growth." (PMID 33420030, 2021).
cancer (13 papers, 2020 to 2025). A tumor composed of atypical neoplastic, often pleomorphic cells that invade other tissues. "In this study, we first characterized the P2RX1 expression and association with outcomes by performing expression and survival analysis of pan-cancer samples from the database." (PMID 35585027, 2022). "The HIVE Lab database lists 86 unique P2RX1 single nucleotide polymorphisms (SNPs) in cells from multiple types of cancer that change the P2X1 receptor protein sequence." (PMID 33125712, 2021). "This indicates that P2RX1 may be associated with an underlying carcinoma." (PMID 35585027, 2022). "Among these non-cancer genes, germline TE insertions in the P2RX1 gene (located on chromosome 17) affected 21 OS patients." (PMID 35013466, 2022). "We evaluated the impact of P2RX1 on cancer prognosis among these 12 human cancers with differential expression of P2RX1 mRNA." (PMID 35585027, 2022). "First, expression data for P2RX1 in pan-cancer were accessed from TCGA and GTEx databases and identified the differential expression of P2RX1 in 22 pairs of human tumors and the corresponding adjacent para-cancerous tissues." (PMID 35585027, 2022). "Similarly, a recent study identifies a unique neutrophil subclone that lacks P2RX1 and participates in immunosuppression and cancer metastasis." (PMID 34312368, 2021). "Analyzing gene expression and prognostic value in TCGA-COAD, we found that TCMM40L, SLC8A1, PPP1R3C, P2RX1 and HMX2 were significantly downregulated in cancer tissues." (PMID 40263288, 2025). "In this study, 33 genes closely related to the Purinergic pathway (such as P2RY8, P2RX1, and GNAS) were selected, and their SNV, CNV, mRNA expression and methylation data were analyzed pan-cancer by bioinformatics methods." (PMID 38180750, 2024). "Therefore, we analyzed the expression pattern of P2RX1 in pan-cancers including BC and its impact on survival and found that the expression level of P2RX1 was lower in BC compared with para-cancerous tissues, and higher P2RX1 expression indicated better prognoses." (PMID 35585027, 2022).
hematologic disorder (1 paper, 2025). A disease involving the hematopoietic system. "P2X receptors perform multiple functions in both normal hematopoiesis and hematologic disorders; for example, P2RX1 and P2X4 may regulate the multipotent fate of hematopoietic stem cells (HSCs)." (PMID 41458092, 2025).
P2RX1 also shares sentences with these, for which no sentence is quoted: infection (4 papers); Hypertension (3); Stroke (3); diabetes (2); dilated cardiomyopathy (2); dry eye (2); Dyskinesia (2); hepatocellular carcinoma (2); leukemia (2); Obesity (2); pancreatitis (2); Parkinson disease (2); prostate carcinoma (2); acute liver failure (1); acute myeloid leukemia (1); acute pancreatitis (1); Alzheimer disease (1); astrocytoma (1); atherosclerosis (1); bacteremia (1); bacterial infection (1); bladder disorder (1); brain disorder (1); breast invasive carcinoma (1); cardiovascular disease (1); colon carcinoma (1); COVID-19 (1); endotoxemia (1); fibromyalgia (1); glioblastoma (1).
A further 17 diseases each share a sentence with P2RX1 in 1 paper.